IL24 (interleukin 24)
Diseases named in the same sentence as IL24 in open-access papers (continued):
Sharing a sentence is not in itself a finding about the gene and the disease.
cancer (continued). "Based on the positive results from pre-clinical and Phase I clinical trials, IL-24 has been transitioned into a phase II clinical trial, indicating that it is has the potential to be safe and effective for cancer gene therapy." (PMID 30424508, 2018). "In one anti-cancer mechanism, IL-24 induces apoptosis through reactive oxygen species (ROS) generation." (PMID 29330517, 2018). "Correspondingly, IL-24 interaction with Sig1R offers a possible novel approach to cancer therapy via targeting IL-24 Sig1R." (PMID 29662489, 2018). "We have previously demonstrated that IL-24 selectively kills cancer cells through p38 mitogen-activated protein kinase (p38 MAPK) signaling." (PMID 30424508, 2018). "Higher IL-24 expression was reported in well and moderate differentiated carcinomas, and expression of IL-24 negatively correlated with lymph node status as in patients with high IL-24 expression fewer lymph nodes were affected." (PMID 29967613, 2018). "IL‐24 inhibits angiogenesis of cancer by suppressing vascular endothelial growth factor, basic fibroblast growth factor, transforming growth factor, and so on." (PMID 28781949, 2017). "IL-24 can also inhibit angiogenesis, promote antitumor immune responses, sensitize cancer cells to radiotherapy-induced killing, and elicit a potent bystander antitumor activity." (PMID 27203744, 2016). "Further, the efficacy of IL-24 as an anti-cancer drug was demonstrated in a Phase I clinical trial using an adenovirus-mda-7 (INGN-241)-based cancer gene therapy approach." (PMID 27602961, 2016). "We also simultaneously introduced IL24 into the oncolytic adenoviral vector since multi-target agents have been widely investigated for cancer treatment." (PMID 27528029, 2016). "Taken together, when combined with TAT and KDEL, IL-24 as a core functional domain shares the mechanisms of adenovirus-mediated intracellular IL-24; it induces cancer cell apoptosis through the ER stress-mediated cell death pathway." (PMID 27203744, 2016). "IL24 is a multifunctional cancer killing cytokine that is a strongly upregulated gene in MSC spheroids." (PMID 26649054, 2016). "We have demonstrated that IL-24 protein generates additional molecules of IL-24, inducing more ER-stress and culminating in an untenable imbalance resulting in apoptosis in cancer cells." (PMID 27271601, 2016). "IL-24 is an immunomodulatory cytokine which can also display broad cancer-specific suppressor effects." (PMID 27271601, 2016). "Our studies define Sigma 1 Receptor as a key initial mediator of IL-24 induction of cancer- specific killing." (PMID 27271601, 2016). "One of these variants, mda-7/IL-24δ2,3,5, induced higher levels of apoptosis in the U2OS cancer cells compared to full-length IL-24 as evidenced by caspase 3 and 7 activation." (PMID 27271601, 2016). "Comparative analysis between stably transfected and transiently transfected IL-24 in cancer cells revealed similar effects on HMGA1 expression." (PMID 27602961, 2016). "Specifically, exogenous IL-24 protein induces growth inhibition and apoptosis only in cancer cells through a mechanism identical to Ad.IL-24 infection." (PMID 27271601, 2016). "IL-24 is a pleiotropic cytokine with effects on numerous cell populations including immune cells, epithelial cells, and cancer cells." (PMID 27271601, 2016). "Several studies have also reported increased sensitivity of human liver, lung, colorectal, cervical, nasopharyngeal and osteosarcoma cancer cells to therapeutic drugs when treated with OAs expressing IL-24." (PMID 27271601, 2016). "The replication-incompetent Ad.IL-24 inhibits cancer cell growth and induces transformed cancer cell-specific apoptosis, as well as generates antitumor responses such as antitumor immune response and the inhibition of angiogenesis." (PMID 27203744, 2016). "We, and others, have shown that delivery of mda-7/IL-24 via an adenovirus vector can efficiently inhibit growth of diverse cancer cells in vivo and in vitro [rev." (PMID 26460950, 2015).
cancer (continued). "Collectively, miRNA regulation of the expression of interleukins (IL-11, IL-1β, IL-24 and IL-32) emerges as a useful tool in probing modulatory mechanisms of cancer promotion/suppression and their (in)direct implication in immunotherapeutic approaches." (PMID 25590298, 2015). "IL-24 is a multifunctional cytokine that is important for B cell differentiation as well as anticancer effects in diverse cancer cells." (PMID 26627005, 2015). "Our studies and others have demonstrated that adenovirus (Ad)-IL-24 induces apoptosis in cancer cells by activating caspase-9, poly (ADP ribose) polymerase (PARP), and JNK." (PMID 26009991, 2015). "New to science, our data show that IL-24 phosphorylation is required for IL-24-mediated anti-cancer activities." (PMID 26009991, 2015). "IL-24 induces cancer selective apoptosis through interacting with endoplasmic reticulum (ER) chaperone protein BiP/GRP78, activating Fas/FasL signaling pathway, as well as reduction in myeloid cell leukemia-1 (Mcl-1) expression." (PMID 26554307, 2015). "Our data provides evidence that IL-24 in combination with CXCR4 inhibitors will be more effective in controlling cancer metastasis." (PMID 25775124, 2015). "We consider that autophagy is a self-protection mechanism against IL-24 induced apoptosis in cancer cells." (PMID 26361755, 2015). "Concurrently, miRNA regulation of the expression of interleukins (IL-11, IL-1β, IL-24 and IL-32) emerges as a useful tool in probing modulatory mechanisms of cancer promotion/suppression and their (in)direct implication in immunotherapeutic approaches." (PMID 25590298, 2015). "We are pioneering approaches to treat advanced CaP that employ conditionally replication-competent oncolytic adenoviruses that simultaneously produce a systemically active cancer-specific therapeutic cytokine, mda-7/IL-24, Cancer Terminator Viruses (CTV)." (PMID 25926554, 2015). "In conclusion, we demonstrated that IL-24 phosphorylation is essential for its anti-cancer properties." (PMID 26009991, 2015). "mda-7/IL-24 displays restricted expression in normal and cancer cells, observed in melanocytes and subsets of T-cells, but not in the majority of normal or cancer cells." (PMID 26460950, 2015). "The present study provides a platform for identifying the phosphorylation site(s) critical for IL-24 to function as an anti-cancer drug." (PMID 26009991, 2015). "Previous studies reported several anticancer functions of IL-24, including cancer-specific induction of apoptosis, cell cycle regulation, and the ability to inhibit angiogenesis." (PMID 26517713, 2015). "Our results provide a platform for identifying the phosphorylation site(s) that are critical for IL-24 to function as an anti-cancer drug." (PMID 26009991, 2015). "The ability of IL-24wt to markedly inhibit β-catenin and cyclin D1 expression and activate GSK-3, determined by its phosphorylation, makes IL-24-based cancer therapy attractive." (PMID 26009991, 2015). "Further, the utility of IL-24 as an anti-cancer drug was demonstrated in a Phase I clinical trial using adenovirus- mda-7 (INGN-241)-based cancer gene therapy approach." (PMID 25775124, 2015). "MDA-7/IL-24 induces cell death via apoptosis and/or toxic autophagy, inhibition of invasion and metastasis, “bystander” anti-cancer activity, radiosensitization, anti-angiogenesis and cancer initiating/stem cell killing." (PMID 26474456, 2015). "The unique features of IL-24 support its further development as an anticancer drug for cancer treatment." (PMID 24377906, 2013). "Although use of IL-24 as an anticancer drug for treatment of cancer is at the forefront, there are numerous questions that remain unanswered." (PMID 24377906, 2013). "Another observation that is in agreement with all of the current reports is that the cellular signaling pathways that are regulated by IL-24 varies in different cancer cells tested and is cell-type dependent." (PMID 24377906, 2013).
cancer (continued). "Although there is substantial sharing of receptors among the members of the IL-10 cytokine family, the biological activities of IL-24, IL-19 and IL-20 are quite distinct with only IL-24 exhibiting receptor-mediated antitumor activity in human cancer cells." (PMID 24377906, 2013). "Enhanced antitumor activity has also been demonstrated when Ad-IL24 was combined with molecularly targeted antisense oligonucleotides, biologic therapy, antioxidants and other novel agents in various types of cancer cells." (PMID 24377906, 2013). "It is also evident that combining with different therapies results in enhanced anticancer activity providing an opportunity for developing IL-24-based personalized therapy for treating patients diagnosed with various types of cancer." (PMID 24377906, 2013). "The study results also suggest that combining IL-24 with activators of apoptosis and autophagy will produce enhanced antitumor activity and will be beneficial in cancer treatment." (PMID 24377906, 2013). "MDA-7/IL-24 was involved in the specific cancer apoptosis through suppression of Bcl-2 expression, which is a key apoptosis regulatory protein of the mitochondrial death pathway." (PMID 22629368, 2012). "Our previous study demonstrates that NSAIDs also induce apoptosis of cancer cells via induction of mda-7/IL-24 expression, leading to enhanced expression of two members of the Growth Arrest and DNA-Damage 45 (GADD45) family." (PMID 21931671, 2011). "We and others have shown that overexpression of mda-7/IL-24 following infection with an adenovirus carrying the mda-7/IL-24 gene induces apoptosis and inhibits cell proliferation in cancer cells." (PMID 21931671, 2011). "High levels of mda-7/IL-24 have been demonstrated to specifically induce apoptosis of cancer cells and therefore mda-7/IL-24 has been referred as a “magic bullet”." (PMID 21931671, 2011). "We have previously reported that induction of apoptosis by NSAIDs is tightly linked to induction of mda-7/IL-24 expression and consequently to GADD45 α and γ upregulation in several cancer cell lines." (PMID 21931671, 2011). "Recently, IL-24 was reported to induce its own expression in cancer cells through mRNA stabilization." (PMID 20072629, 2010). "Transient intracellular over-expression of IL-24 by methods other than viral delivery should therefore result in increased cancer cell death provided that IL-24 itself has the ability to specifically initiate events necessary for apoptosis." (PMID 18074024, 2007). "Despite this advanced stage of clinical testing many fundamental questions regarding the tentative IL-24-mediated selective killing of cancer cells remain to be answered." (PMID 18074024, 2007). "These astonishing attributes have served as a basis for the development of a therapeutic adenovirus delivering IL-24 (Ad-IL-24) to cancer patients, a form of treatment that is currently being assessed in clinical trials (Introgen company homepage)." (PMID 18074024, 2007). "Nevertheless, several studies converge on an UPR (unfolded protein response) or ER (endoplasmic reticulum) stress response, triggered by a temporal over-expression of recombinant IL-24 in the ER, which eventually promotes apoptosis of cancer cells." (PMID 18074024, 2007). "Over the past decade numerous publications have argued that IL-24, an IL-10-family cytokine, selectively kills a vast variety of cancer cells, in vivo and in vitro, leaving healthy cells unharmed (for recent reviews:)." (PMID 18074024, 2007). "Hek cells served as a non cancer control cell line that should be resistant to IL-24-mediated killing." (PMID 18074024, 2007). "Consequently, multiple studies highlight IL‐24 as a viable “anti‐cancer” therapeutic, with successful outcomes observed in combination therapies involving small molecule inhibitors, chemotherapeutic drugs, and radiation." (PMID 40338095, 2025). "IL-24 plays a significant role in immune responses, particularly in cancer." (PMID 40607413, 2025).
cancer (continued). "Additional investigation also confirmed the bystander effect of IL‐24 in various cancer types." (PMID 40338095, 2025). "In addition to its involvement in cancer cell death, IL‐24 also hampers cell migration and invasion through the downregulation of crucial factors such as MMPs, specifically MMP‐2 and MMP‐9, PI3K, FAK, and the CXCR4 chemokine." (PMID 40338095, 2025). "Notably, recognizing GSK3β inhibition as a crucial mechanism driving IL-24-mediated cancer-specific apoptosis greatly enhances its therapeutic potential in oncology." (PMID 40072085, 2025). "Similarly, IL‐24 secreted from P69 (normal prostate epithelial cells), when administered to the cancer cell lines DU‐145, BxPC‐3, led to the repression of colony forming abilities and invasiveness." (PMID 40338095, 2025). "In addition to the standard cytokines, other molecules, such as IL-4, IL-9, and IL-24, are of research interest; they seem to act at different levels of the anti-cancer immune axis." (PMID 40722601, 2025). "IL24’s efficacy has been demonstrated in Phase I clinical trials for several advanced cancers." (PMID 40175348, 2025). "ER stress renders cancer cells more vulnerable to IL-24–mediated toxic effects." (PMID 39744942, 2025). "Information pertaining to the immunoregulatory role of IL‐24 is limited in the context of cancer." (PMID 40338095, 2025). "While the precise mechanisms behind its cancer cell-specific cytotoxicity are still under investigation, our findings suggest that TXNIP might inhibit cancer cell growth and survival by activating IL-24 signaling." (PMID 40175348, 2025). "Thus, developing improved strategies to overcome these technical difficulties would significantly advance IL‐24‐based therapy for cancer." (PMID 40338095, 2025). "Adenovirus overexpressing IL‐24 also increased the expression of acid sphingomyelinase (ASMase), an enzyme catalyzing the hydrolysis of sphingomyelin into ceramide, resulting in increased ASMase activity and reduced sphingomyelin levels in cancer cells." (PMID 40338095, 2025). "The connection between mda‐7/IL‐24 expression and disease pathology across cancer types." (PMID 40338095, 2025). "The impact of IL-24 on cancer stem cells (CSCs) has been recently investigated." (PMID 40806452, 2025). "We hypothesize that GSK3β, a multifunctional kinase involved in cancer progression and cancers resistant to radio-, chemo- and targeted therapy, might play a role in the anti-cancer-specific function of IL-24." (PMID 40072085, 2025). "The role of IL-24 in B cell function is still being actively studied, especially in cancer, with research suggesting that it may influence both B cell activation and regulation." (PMID 40607413, 2025). "Third, although our findings indicate that TXNIP may suppress cancer cell growth through IL-24 signaling, the exact mechanisms remain unclear and require further investigation." (PMID 40175348, 2025). "IL-24 antiangiogenic activity was tested in several in vitro and in vivo cancer cell models." (PMID 40806452, 2025). "We and others have previously demonstrated that IL-24 leads to apoptosis in cancer cells by endoplasmic reticulum (ER) stress activation, reactive oxygen species (ROS) accumulation, p38 MAPK activation, mitochondrial dysfunction, and ceramide production, while not affecting normal cells." (PMID 40072085, 2025). "IL-24 induces toxic autophagy and apoptosis in a cancer-selective manner." (PMID 39744942, 2025). "Notably, IL-24’s cytotoxicity in cancer cells can also occur independently of receptor engagement, further highlighting its selective action toward malignant cells." (PMID 40607413, 2025). "In this regard, it has been observed that PTMs are crucial for IL‐24 anti‐cancer activity." (PMID 40338095, 2025). "Evidence suggests that IL24 (also known as MDA‐7) may represent a promising cancer therapeutic agent in further studies, while research on IL24 delivery with multiple routes is undergoing continued clinical development (INGN‐241)." (PMID 38737469, 2024).
cancer (continued). "IL24 modulates immune response by enhancing immune cell activity against cancer cells." (PMID 39850884, 2024). "Additionally, IL24 increases cancer cell sensitivity to chemotherapy and radiation, enhancing their effectiveness." (PMID 39850884, 2024). "IL24 selectively induces apoptosis in a variety of cancer cell types, sparing normal cells." (PMID 39850884, 2024). "In contrast, the WNT5A+ inflammatory fibroblast interacts with cancer cells via IL24:IL20RA and WNT5A:FZD5 pathways, which could promote cancer progression and chemoresistance." (PMID 38744958, 2024). "Interleukin-24 (IL-24)/Melanoma differentiation-associated gene-7(Mda-7) is a special member of the IL-10 family of cytokines that can specifically cause apoptosis in cancer cells without affecting healthy cells." (PMID 37280571, 2023). "Five alternatively spliced isoforms of IL-24 induce apoptosis in cancer cells." (PMID 37444474, 2023). "Based on the signal transduction pathways that IL-24 can activate in cancer cells, it is possible to speculate that IL-24 could induce the expression of a more stable and active truncated isoform of SOCS3." (PMID 37444474, 2023). "IL-24, by triggering ER stress, increases ceramide levels in cancer cells via PERK activity." (PMID 37444474, 2023). "In recent years, it has been shown that IL-24 interacts with chaperones in the endoplasmic reticulum, binding immunoglobulin protein (BiP) and sigma 1 receptor (σ1) when IL-24 triggers apoptosis in cancer cells." (PMID 37444474, 2023). "Mechanistically, both secreted and intracellular expressions of IL-24 in cancer cells mediated apoptosis through JAK/STAT-independent and p38 MAPK-dependent pathways and induced sustained ER stress as evidenced by expression of ER stress markers (BiP/GRP78, GRP94, XBP1, and eIF2α)." (PMID 37444474, 2023). "Exogenous IL-24 activates PERK during ER stress in different cancer cells." (PMID 37444474, 2023). "Also, based on the positive results from pre-clinical and Phase I clinical trials, IL-24 has been transitioned into a phase II clinical trial, indicating that it has the potential to be safe and effective for cancer gene therapy." (PMID 37280571, 2023). "In advanced cancer patients, Ad-IL-24 was able to inducedapoptosis in all tumors." (PMID 36206378, 2022). "Moreover, we have established and validated the use of a new recombinant bacteria B.breve-IL-24 gene for cancer therapy in vivo." (PMID 35814447, 2022). "The well-known biological role of IL-24 is to inhibit proliferation and promote apoptosis in a broad spectrum of cancer cells, and phase I clinical trial results suggested that a recombinant adenovirus overexpressing MDA-7/IL-24 (INGN-241) has shown certain clinical benefits for patients." (PMID 36100847, 2022). "IL-24 is documented to inhibit growth and promote apoptosis in cancer cells." (PMID 35915803, 2022). "Upregulation of IL24 is able to induce apoptosis selectively in many cancers and xenograft models." (PMID 35984577, 2022). "An additional attribute of MDA-7/IL-24, and perhaps the one most applicable from a translational perspective is the ability to synergize with standard of care therapeutics, e.g., radiation and chemotherapy, promoting cancer cell death." (PMID 35402258, 2022). "Therefore, many scientists regard IL24 as a promising molecular therapy for cancers and apply it in the phase I clinical trial." (PMID 34955744, 2021). "MDA-7/IL-24 overexpression leads to up-regulation of pro-apoptotic genes such as Bax, Bad and others and downregulation of anti-apoptotic genes such as Bcl-xL and Bcl-2 in cancer cells." (PMID 35008495, 2021). "Accordingly, we determined whether Ad.5-TCTV infection of cancer cells instigated similar molecular pathway alterations as previously observed when mda-7/IL-24 was delivered via an Ad.5-CTV." (PMID 33670594, 2021).